MLKL (mixed lineage kinase domain like pseudokinase)
Diseases named in the same sentence as MLKL in open-access papers (continued):
Sharing a sentence is not in itself a finding about the gene and the disease.
cancer (continued). "An increasing number of studies have demonstrated that downregulation or mutations of necroptosis regulators including RIPK1, RIPK3, MLKL and CYLD are frequently found in human tumors, which indicates the pivotal roles of necroptosis in the pathogenesis of cancer." (PMID 30005626, 2018). "The antitumor activity of MLKL-mRNA treatment might be further improved when combined with cancer treatment options that are already clinically established such as checkpoint blockade approaches." (PMID 30143632, 2018). "Furthermore, by combining HRs from studies using Cox multivariate analysis, we found that MLKL was an independent prognostic factor of OS in cancer patients." (PMID 30005626, 2018). "In the future, more relevant studies are warranted to investigate the role of MLKL in human cancer." (PMID 30005626, 2018). "Recent studies have demonstrated that MLKL could serve as a potential prognostic biomarker for cancer patients." (PMID 30005626, 2018). "Recent studies have revealed that MLKL could serve as a potential prognostic biomarker for patients with cancer." (PMID 30005626, 2018). "Therefore, we performed the current meta-analysis to elucidate the prognostic and clinicopathological significance of MLKL expression in patients with cancer." (PMID 30005626, 2018). "Recent studies have demonstrated that MLKL could serve as a potential prognostic biomarker for patients with carcinoma." (PMID 30005626, 2018). "Therefore, we next addressed whether cancer immunotherapy with ICI also relies on the activity of RIPK3 as a component of the necroptosis pathway upstream of MLKL." (PMID 40345706, 2025). "Lately, the importance of immunogenic cell death (ICD) for killing cancer cells has emerged, and expression of proteins that activate this kind of cell death (such as MLKL) or co-administration with molecules that enhance ICD (such as vitamin C) could also result in a better antitumor outcome." (PMID 37016144, 2023). "In addition, MLKL might influence cancer progression and metastasis via both necroptosis-dependent and non-dependent function." (PMID 37061535, 2023). "Furthermore, high MLKL expression was negatively correlated with histological grade and lymphatic metastasis, which indicates MLKL-induced necroptosis may be the target of cancer treatment." (PMID 37169000, 2023). "However, RIPK3 is not universally expressed in many cancer cells; thus, MLKL, a final executioner of necroptosis signaling pathway, could be a potential target in these type of cancer cells." (PMID 36361505, 2022). "On the other hand, MLKL may play a role in cancer through functions beyond necroptosis." (PMID 35422482, 2022). "Among them, the synergy with ferroptosis, further RIPK1/RIPK3/MLKL studies, the mechanism and translational applications with inflammation and oxidative stress, and the therapeutic potential to treat cancer and neurodegenerative diseases might be the rising and promising research areas." (PMID 35769473, 2022). "Therefore, loss of RIPK3 and MLKL expression as observed in many cancer cells would likely not compromise the MLKL-mRNA approach described here." (PMID 30143632, 2018). "Our results demonstrated that decreased expression level of MLKL was significantly associated with poor overall survival (OS) (pooled HR 0.26, 95%CI 0.17–0.40, high/low) and event-free survival (EFS) (pooled HR 0.45, 95%CI 0.23–0.87, high/low) in cancer patients." (PMID 30005626, 2018). "Here we performed current meta-analysis to explore the prognostic value of abnormally expressed MLKL and the relation between MLKL expression levels with clinicopathological characteristics as well as to further reveal the prognostic value of necroptosis in cancer patients." (PMID 30005626, 2018). "Hence, inhibition of RIPK and MLKL-dependent necroptosis may be advantageous for evasion of immune surveillance and cancer growth." (PMID 25675296, 2015).
cancer (continued). "Collectively, these results support the notion that the lower the levels of active MLKL expression in CRC cells are, the less viable the cells are, the less deadly respective cancers become, the longer patients survive." (PMID 39979285, 2025). "Another explanation could be because cancer cells often have dysregulated cell death pathways, and blocking one pathway could cause Ad[CE1A] to induce cell death via another pathway, ensuring that the virus kills the host cell and spreads despite MLKL inhibition." (PMID 40247106, 2025). "Necrosulfonamide, as an inhibitor of necroptosis, exerts its action by targeting mixed lineage kinase domain-like protein (MLKL), which is pivotal in initiating necroptosis and triggering apoptosis in cancer cells." (PMID 38728242, 2024). "MLKL and RIPK3 are vital for the induction of necroptosis and are known to be suppressed or altered in many cancers." (PMID 38893185, 2024). "Another study found that TNF-α and IFN-γ were able to induce PANoptosis in 13 different human cancer cell lines from colon, lung, melanoma, and leukemia, through the activation of GSDMD, GSDME, caspase-8, caspase-3, caspase-7 and MLKL." (PMID 38877579, 2024). "Compared MscL with MLKL or GSDMD, it has more simple mechanism and specific activation, making it easy for non-invasive cancer treatment by ultrasound." (PMID 36936526, 2023). "Our findings showed that many important necroptosis molecules in the pan-cancer, including PLK1, MLKL, FASLG, and ZBP1, demonstrated a high level of activation in the apoptosis signaling pathway." (PMID 37000317, 2023). "The results showed that MLKL had a strong positive correlation with CASP8, ZBP1, FASLG, RIPK1, and RIPK3 in all 33 cancer types, and RIPK3 was also strongly correlated with CASP8, MLKL, and ZBP1." (PMID 37000317, 2023). "Our findings showed that MLKL was positively correlated with the expression of immune checkpoints such as PD1, PD-L1, PD-L2, and CTLA4 in most cancer types, except for ICOSLG, CD200, CEACAM1, HHLA2, and VTCN1 in BUC." (PMID 37000317, 2023). "Our result identified the FADD, TNFRSF1A, CASP9, MLKL, and CASP4 involved in the PANoptosis process and significantly affect patient survival, which can provide future direction in cancer research." (PMID 36874021, 2023). "In 16 HER2-positive cancers, tumors with increased mean of positive pixels on PostcontrastT1 at SSF 2 showed the upregulation of MLKL (log2FC = 2.2; P < 0.001), compared with those with decreased mean of positive pixels." (PMID 37391754, 2023). "Previous studies have indicated that cancer cells eradicate necroptosis by downregulating NRGs to evade necroptosis-induced cell death mainly involving RIP1, RIP3, and MLKL." (PMID 36092932, 2022). "Downregulation of expression of several key necroptosis mediators in cancer has been reported, such as CYLD, MLKL, and RIPK3." (PMID 36065304, 2022). "Through differential expression analysis, we found that MLKL was highly expressed in CRC tissues, while RIPK1 and RIPK3 were lowly expressed in cancer tissues." (PMID 36544770, 2022). "In comparison, FADD in 12 cancer types, FASLG in 3 cancer types, RIPK1 in 19 cancer types, TLR3 in 25 cancer types, TNF in 11 cancer types, FAS in 22 cancer types, MLKL in 15 cancer types, and RIPK3 in 12 cancer types had homozygous deletions." (PMID 35748782, 2022). "Little is known about MLKL, the executioner activated by RIPK3 during necroptosis, and its opposing roles in cancer." (PMID 35422482, 2022). "Some cancer cells escape from necroptosis by decreasing the expression of key necroptosis mediators, including CYLD, RIPK3, and MLKL." (PMID 35864548, 2022). "Our results provide valuable information toward a better understanding of necroptosis, MLKL in CCA, and for a potential cancer immunotherapy as well as novel prognostic markers." (PMID 34083572, 2021).
cancer (continued). "Some of these genes (e.g. CENPF, MLKL, TFDP1, MCF2L) have a known influence on cancer, while others (e.g. NUP54, BBS1 and HTT) have been superficially studied under the tumoral context." (PMID 34316711, 2021). "On the contrary, double knocked out cells RIP3/FADD and MLKL/FADD were sensitive and RIP3/FADD revealed the highest sensitivity of all cell lines to treatment with anti-cancer drugs." (PMID 33800107, 2021). "Last but not least, aurora kinase inhibitor CCT137690 can indirectly activate RIPK1, RIPK3, and MLKL in PDAC in vivo, which leads to the initiation of necroptosis and the inhibition of cancer growth and metastasis." (PMID 33665167, 2020). "We found that depletion of MLKL enhances TRAIL and TNFα-induced apoptosis in various cancer cell lines and with the enhancement of cell death being RIP3-independent." (PMID 32917855, 2020). "Moreover, PUFA treatment on cancer cells induced lipid peroxidation-dependent necroptosis evidenced by elevated phosphorylation of RIP3 and MLKL, which was blocked by Fer-1." (PMID 39426958, 2024). "Additionally, prunetin (PRU), an O-methylated flavonoid, can be used to treat gastric cancer, as it can inhibit cancer cell proliferation through necroptosis by activating RIPK3 and phosphorylating MLKL." (PMID 38684668, 2024). "Moreover, increasing research show that miRNAs participate in the necrotic pathway via targeting key regulators such as MLKL and RIP3 in all kinds of cancers, including colon cancer." (PMID 36065304, 2022). "Meanwhile, homozygous CNV analysis showed that FADD in 22 cancer types, FASLG in 25 cancer types, RIPK1 in 22 cancer types, TLR3 in 15 cancer types, TNF in 23 cancer types, FAS in 15 cancer types, MLKL in 12 cancer types, and RIPK3 in 17 cancer types had homozygous amplifications." (PMID 35748782, 2022). "It is not surprising that RIPK1, RIPK3, and MLKL in cancer play a central role in modulating necroptosis." (PMID 33567618, 2021). "The inhibition of necroptosis through downregulation of its main driver (RIPK1, RIPK3, and MLKL) has been observed in different cancer types, showing in some cases also a negative impact on patient survival." (PMID 34745951, 2021). "In cancer cells, RIPK3 interacts with and phosphorylates MLKL to promote necroptosis." (PMID 30005626, 2018). "To gain insight into the mechanism by which VP + SF eliminates cancer cells, we evaluated the expression of key proteins involved in apoptosis (PARP, caspase 3, and caspase 9), autophagy (Beclin-1 and p62), and necroptosis (RIP1 and MLKL)." (PMID 29201061, 2017). "However, decreased mRNA expression was observed for MLKL, STAT3, and HIF-1α in cancer cells." (PMID 41463386, 2025). "MLKL, as an executor of necroptosis, may influence cancer progression and metastasis via necroptosis-dependent and non-dependent functions." (PMID 37061535, 2023). "In that case, the application of the RIP3 or MLKL inhibitors to the cells with non-functional FADD might support the effect of anti-cancer drugs on the principle of synthetic lethality." (PMID 33800107, 2021). "Inhibitors of heat shock protein 90 (HSP90), a molecular chaperone controlling the RIPK3 and MLKL stability and function, such as kongensin A, 17AAG, IPI-504 and Alvespimycin (17-D MAG), both in clinical trials in cancer patients, may indirectly impair necroptosis." (PMID 33050394, 2020). "Various cancer cells (either in the presence or absence of MLKL knockdown) completely lost their sensitivity to TRAIL when treated with the pan-caspase inhibitor zVAD; lack of necroptotic cell death is consistent with the fact that these cells lack RIP3 expression." (PMID 32917855, 2020). "The expression of MLKL in UC3 cells with combinatorial treatment was significantly higher than cells with individual treatment of melatonin or VPA, indicating that combinatorial treatment with melatonin and VPA could be a potential cancer therapeutic." (PMID 28593135, 2017).
cancer (continued). "However, the downregulation of necroptotic factors may not occur in all cancers: high expression of RIPK1 or MLKL has been reported to predict worse prognosis for some cancer patients, both in melanoma and breast tumors." (PMID 37628814, 2023). "In light of this, our findings that RAF, MEK, PI3K and EGFR inhibitors did not cooperate with MLKL in killing CRC cells are not surprising since these agents promote, rather than inhibit, autophagy in various cancer cell types, including CRC cells." (PMID 39979285, 2025). "Upon co-culture with fluorescently labeled MOC1 cells undergoing TSZ-induced necroptosis, BMDMs showed increased uptake of carcinoma cell debris, which was completely absent with RIPK3–/– or MLKL–/– carcinoma cells." (PMID 40345706, 2025). "In general, MLKL has been reported to be upregulated upon IFN stimulation for type I and II IFNs in cancer cells, but so far, no type I IFN–mediated upregulation of MLKL in human fibroblasts was reported." (PMID 38400065, 2024). "Although MLKL showed no differential expression between the NRGPI subgroups, it was the only differentially expressed core necroptotic mediator in cancer samples as compared to normal tissues." (PMID 36389725, 2022). "Unlike RIPK3 and MLKL, RIPK1 expression is positively correlated with cancer development." (PMID 39872161, 2022). "Finally, combination M + E + F increased the levels of AIF, P62, MLKL, p-MLKL, RIP3, and p-RIP3 in HCT116 cells (p < .05) but not in HDF cells, suggesting that autophagy and necroptosis levels were also increased in the treated cancer cells." (PMID 36588385, 2023). "These screen results were validated by testing 23 randomly selected cancer cell lines, which showed a complete resistance to TSZ- and TNFα+Cycloheximide+zVAD.fmk (TCZ)-induced necroptosis, lack of RIPK3 expression, and lack of MLKL Ser358 phosphorylation upon stimulation with TSZ treatment." (PMID 30157175, 2018). "Importantly, transcriptomics analysis of the screened 941 cancer cell lines revealed that high AXL and TYRO3 mRNA levels predict both resistance to necroptosis and low RIPK3 mRNA levels, but not those of RIPK1, MLKL, or any other pro-necroptotic genes." (PMID 30157175, 2018).
infection (115 papers, 2015 to 2026). The state of being infected such as from the introduction of a foreign agent such as serum, vaccine, antigenic substance or organism. "In contrast, in Sp140−/− mice on the C57BL/6 background, which express high levels of type I IFN after Mtb infection and develop necrotic pulmonary lesions, MLKL-deficiency reduced bacterial burden and pathology after high-dose infection." (PMID 40950000, 2025). "TBEV-infection caused severe hepatic inflammation and activated the MLKL pathway, a known valproate-induced death mechanism." (PMID 38570685, 2024). "A deficiency of caspase-1/11 or MLKL led to a slight delay in cell death at the early stage of infection, but they were largely dispensable at later stages." (PMID 36852999, 2023). "In order to examine the role of necroptosis on CD8+ T cell number and function during chronic LCMV infection, we infected RIPK3 and MLKL-deficient animals and performed analyses at days 8 and 35 post infection." (PMID 36792599, 2023). "Knockdown of two proteins (EFTUD2 and SNRNP200) belonging to the U5 snRNP family resulted in a reduction of p-MLKL after infection of L929 cells with reovirus T3DS (reovirus variant derived from the Lemay lab)." (PMID 36768641, 2023). "In agreement with the in vivo data, both expression of OTUB1 and deletion of MLKL in OTUB1-deficient HepG2 cells reduced LDH release upon infection with Lm and stimulation with TNF." (PMID 33712742, 2021). "As we observed a disruption of cell monolayer and a possible induction of phosphorylated MLKL upon super-infection, we linked our findings more to necroptosis." (PMID 33333815, 2020). "Consistently, in present study we found ΔsopB infection induced an increased level of MLKL phosphorylation in cells of cecum associated with increased inflammation and bacterial translocation." (PMID 31024858, 2019). "Following ΔsopB infection for 2 days, there was a significant decrease in the weight of cecum, however, MLKL deletion improved the loss of cecum weight." (PMID 31024858, 2019). "The cell lysis induced by active MLKL releases massive intracellular damage-associated molecular patterns, such as interleukin-1α, ATP, genomic and mitochondrial DNA, which lead to inflammation and recruitment of immune cells to the sites of infection." (PMID 38292869, 2024). "Necroptosis is a form of modulated necrosis that is stimulated downstream of TNFR1; relies on the activity of RIPK1 and RIPK3; is mediated by the mixed-lineage pseudokinase MLKL; and may be caused by mechanical damage, inflammation, or infection." (PMID 36632211, 2023). "Indeed, they suggest that dysregulation of necroptosis upstream of MLKL, whether leading to either impairment or enhancement of cell death may be associated with immune abnormalities that alter susceptibility to infection." (PMID 32358523, 2020). "While total RIP3 expression was not affected, the cardiomyocytes exhibited a strong increase in RIP3 phosphorylation 24 h post-infection, while MLKL phosphorylation remained unaltered." (PMID 41550884, 2026). "The phosphorylation level of receptor-interacting protein kinase 3 (RIP3) was elevated post-infection with SARS-CoV-2 while phosphorylation of mixed lineage kinase domain (MLKL)-S358 remained unaltered." (PMID 41550884, 2026). "To further confirm if the upregulation of MLKL during the early stages of infection was dependent on RIPK3, we conducted the time course experiment in a RIPK3‐deficient cell line HeLa." (PMID 40490945, 2025). "Consistent with constrained necroptosis execution, MLKL expression remained minimal throughout infection, while AIFM1 decreased progressively, confirming parthanatos suppression." (PMID 41568347, 2025). "While ΔespL infection triggered comparable MLKL phosphorylation between WT, Tnfr1−/− and TrifLps2 macrophages, caspase-1 processing, GSDMD cleavage and macrophage lysis were reduced in TrifLps2 macrophages compared to WT and Tnfr1−/− macrophages." (PMID 40128366, 2025).